TLR4 (toll like receptor 4)
Diseases named in the same sentence as TLR4 in open-access papers (continued):
Sharing a sentence is not in itself a finding about the gene and the disease.
Sepsis (continued). "We studied the mechanism underlying the effect of sesamin on the pathophysiology of sepsis through the HMGB1/TLR4/IL-33 signalling pathway." (PMID 32893702, 2020). "TLR2 Arg753Gln: AG genotypes and A allele; TLR4 Asp299Gly: CT genotype and C allele; TLR4 Thr399Ile AG genotype and A allele showed significant higher risk to sepsis as compared to other genotypes and alleles." (PMID 33247673, 2020). "In people, platelet TLR4 expression is elevated during sepsis and this upregulation is associated with the severity of sepsis-induced thrombocytopenia." (PMID 31307465, 2019). "It is proposed that an occult variable in experiments where morphine is being proposed to activate TLR4 is actually underlying sepsis induced by the opioid." (PMID 31921165, 2019). "In another in vivo sepsis model, transfusion of TLR4 deficient platelets in platelet-depleted mice attenuated microvascular thrombosis." (PMID 31307465, 2019). "Recent evidence has shown that TLR4 deficiency increases resistance in sepsis-induced immune dysfunction." (PMID 31234591, 2019). "Gram-negative bacterial endotoxin, lipopolysaccharide (LPS) is recognized by toll-like receptor 4 (TLR4) on macrophages and implicated in the pathogenesis of sepsis." (PMID 31480519, 2019). "It has been proved that TLR4-mediated innate immunity and inflammatory response play an important role in the dysfunction of cardiomyocyte caused by sepsis." (PMID 29440462, 2018). "Previous studies using simple IAH models reported that intestinal bacterial translocation and Toll-like receptor 4 were the underlying mechanisms of IAH-derived sepsis." (PMID 29196339, 2018). "In‐depth research on HMGB1 has shown that HMGB1 is associated with TLR4‐mediated inflammatory response and a variety of diseases, such as sepsis and gliomas." (PMID 29670828, 2018). "Animal studies suggest that platelet TLR-4 is involved in the development of sepsis-associated thrombocytopenia." (PMID 29734352, 2018). "The researchers also linked this activity to sepsis, a disease that is commonly associated with platelet TLR4." (PMID 29170605, 2017). "Melioidosis patients showed significantly down regulated expression of TLR4 while both TLR2 and TLR4 was down regulated in septicaemic melioidosis cases compared to sepsis caused by other pathogens." (PMID 28628607, 2017). "Among the diseases caused by TLR4 abnormal activation by bacterial endotoxin, sepsis is the most dangerous one because it is a life-threatening acute system inflammatory condition that still lacks specific pharmacological treatment." (PMID 28976923, 2017). "TLR2 and TLR4 were significantly up regulated in sepsis caused by other pathogens compared to healthy controls." (PMID 28628607, 2017). "Significantly, more overall previous episodes of infection, higher proportion of previous SBP episodes, and severe sepsis cases were observed in TLR4+896A/G and CD14-159C/T variant allele carriers than wild-type carriers." (PMID 27861595, 2016). "In variant TLR4+896 allele carriers with severe sepsis, a significantly positive correlation was noted between LPS-stimulated TLR4 expression and corresponding TNFα/nitrite production." (PMID 27861595, 2016). "Odds ratios (ORs) and 95% confidence interval (95% CIs) were calculated to evaluate the association of toll like receptor 4 gene polymorphisms rs4986790 and rs4986791 with sepsis risk." (PMID 27958344, 2016). "Corresponding to the enhanced LPS-stimulated TNFα/nitrite production, the significantly up-regulated NFκBp65, p-iNOS and p38MAPα mRNA and protein expressions were found on cultured monocyte of TLR4+896A/G variant allele carriers and severe sepsis cases." (PMID 27861595, 2016). "In supernatant on cultured CD16+ monocytes of variant TLR4+896A/G allele carriers and severe sepsis cases, significantly higher baseline and LPS-stimulated TLR4 over-expression was accompanied by TNFα and nitrite over-production." (PMID 27861595, 2016).
Sepsis (continued). "For TLR4+896A/G variant allele carriers with severe sepsis, high plasma endotoxin/IL-10 inhibits HLA-DR expression and impaired phagocytosis were noted in their classical monocyte." (PMID 27861595, 2016). "More recent studies have shown a single nucleotide polymorphism rs11536889 in 3′-untranslated region of TLR4 associating with periodontitis and organ failure in sepsis." (PMID 27293318, 2016). "S100A8/A9 has been shown to be an endogenous ligand of Toll-like receptor-4 (TLR-4), to be associated with human sepsis and endotoxemia, and to play an important role in innate immunity." (PMID 27537874, 2016). "Significantly, higher plasma endotoxin and IL-10 levels were observed in cases carrying variant TLR4+896A/G allele and severe sepsis." (PMID 27861595, 2016). "Accordingly, it was reasonable to observe a significant negative correlation between plasma endotoxin levels and LPS-stimulated CD16- (classical) monocyte HLA-DR expression in our TLR4+896A/G or CD14-159C/T variant allele carriers with severe sepsis." (PMID 27861595, 2016). "In univariate analysis, the odd ratio for predicting severe sepsis among TLR4+896A/G variant allele carriers was 2.41 whereas 1.82 for CD14-159C/T variant allele carriers." (PMID 27861595, 2016). "High plasma endotoxin/IL-10-related HLA-DR down-regulation and impaired phagocytosis of CD16- (classical, phagocytic) monocytes also resulted in increased severe sepsis risk among TLR4+896A/G and CD14-159C/T variant allele carriers." (PMID 27861595, 2016). "Among all cases, 59% of TLR4+896A/G variant allele carriers complicated with severe sepsis whereas 43% of CD14-159C/T variant allele carriers complicated with severe sepsis." (PMID 27861595, 2016). "It is important in terms of clinical value and theoretical significance to get clearer perspective on the relationship of toll like receptor 4 gene polymorphisms rs4986790 and rs4986791 with sepsis risk." (PMID 27958344, 2016). "Considering those discrepancies, we performed this meta-analysis to comprehensively analyze the associations of the rs4986790 and rs4986791 polymorphisms in toll like receptor 4 gene with sepsis susceptibility involving 51 relevant case-control studies." (PMID 27958344, 2016). "An anti-TLR4/MD2 monoclonal antibody (mAb) was also shown to decrease lethality in a model of polymicrobial sepsis caused by implantation of a stent in the cecum of mice." (PMID 26147469, 2015). "Because overwhelming activation of TLR4 signaling underlies the pathogenesis of sepsis, various TLR4 antagonists have been developed and some have entered clinical trials." (PMID 25766838, 2015). "Pre-treatment with anti-TLR2 or anti-TLR4 mAb alone showed significant protection from sepsis-associated death." (PMID 26147469, 2015). "Preventive treatment with mAbs targeting either TLR2 (T2.5) or TLR4 (1A6) caused a significant improvement in the survival rate during severe sepsis compared to the isotype control group, where 100% of the mice subjected to CLP succumbed within 24 hours." (PMID 26147469, 2015). "Previous studies by our group showed that either TLR2- or TLR4-deficient mice display improved bacterial clearance and reduced mortality during polymicrobial sepsis." (PMID 26147469, 2015). "Even though several TLRs are known to cause sepsis, the vast structural and functional information make TLR4 the most attractive target and TLR2 the next favorite for anti-sepsis treatment." (PMID 26198237, 2015). "For example, the expression of TLR4 in renal tubules, glomeruli, and peri-tubular capillaries is increased after sepsis, and mice deficient in TLR4 have a reduced increase in blood urea nitrogen (BUN) when subjected to LPS." (PMID 25182709, 2014). "Sepsis caused severe endothelial swelling and decreased glomerular fenestration, both of which were reduced by TLR4 inhibition." (PMID 25182709, 2014).
Sepsis (continued). "In sepsis, Castoldi and colleagues recently showed that TLR4-deficient mice had reduced renal neutrophil activation and infiltration compared with wild-type mice and that neutrophil depletion improved renal function." (PMID 25182709, 2014). "Lipopolysaccharide-induced sepsis has been associated with TLR4 signalling pathway which in collaboration with the JAK/STAT signalling regulate endotoxemia and inflammation." (PMID 25255432, 2014). "This study assesses the validity of the assumption that a well-known regulatory TLR4 polymorphism influences the outcome of sepsis among adults." (PMID 24950711, 2014). "According to these results, it would be worthwhile to further assess the TLR4 rs11536889 polymorphism for its relevance to sepsis in larger and independent cohorts." (PMID 24950711, 2014). "Our results demonstrate that statistically significant associations with risk of sepsis were observed for the candidate rs11536889 SNP of TLR4 gene, rs2563298 SNP of CD14 gene and two haplotypes." (PMID 25394369, 2014). "Lipopolysaccharide (LPS), which is closely associated with infectious diseases such as sepsis and periodontal diseases, is a cell wall component of Gram-negative bacteria and it is recognized by macrophages via Toll-like receptor 4 (TLR4)." (PMID 24040305, 2013). "The resulting MD2/LPS complex triggers a TLR4-mediated signaling process by binding to the TLR4 extracellular domain, leading to nuclear factor-kB activation, which causes acute and severe inflammation and sepsis." (PMID 22363519, 2012). "In an Intensive Care Unit population at risk for sepsis the TLR4 SNPs were present in a higher frequency when compared to a control population." (PMID 23730203, 2012). "Two nonsynonymous TLR4 SNPs (rs4986790 and rs4986791) have been shown to be associated with sepsis and infectious diseases in Caucasians and Africans." (PMID 21219635, 2011). "Supporting our results, it has been recently found that severe sepsis and septic shock is associated with decreased expression of TLR4 on host immune cells." (PMID 20525286, 2010). "The relationship between gene polymorphisms in TLR1, TLR2, TLR4 and sepsis, and MODS has been well studied." (PMID 21274447, 2010). "For risk associations with severe sepsis we compared the SNP carriers (41 heterozygous TLR4, and 10 homozygous and 75 heterozygous carriers of the TIRAP/Mal-SNP) with WT-patients (n = 240)." (PMID 20525286, 2010). "In contrast to data describing TLR downregulation after LPS in vitro, murine sepsis is associated with an increased TLR4 protein expression in tissue." (PMID 19371402, 2009). "While wild type Y. pestis causes sepsis and mortality in a mouse model of infection, the expression of TLR4-stimulatory LPS resulted in containment of the infection by the innate immune response and less efficient systemic spread of the infection." (PMID 19169359, 2009). "Binding of the LPS/MD-2 complex to TLR4 causes TLR4 dimerization, and results in the activation of NF-κB leading to acute and severe inflammation and sepsis." (PMID 19816595, 2009). "DEX could attenuate AKI through KDM5A inhibition in sepsis, transcription and protein levels of genes such as TLR4, MYD88, MTA1, PTGS2, CASP3 associated with NF-κB signaling pathway were all compromising after treated with DEX." (PMID 40989844, 2025). "Moreover, CD16 +monocytes isolated from patients with sepsis had high levels of TLR4-TIR acetylation that was associated with a pro-inflammatory gene profile." (PMID 40512027, 2025). "Signal transduction studies showed that the activation of TLR4, an essential component of the innate immune system, by sepsis causes downstream enhancement of PI3K/MAPK signaling, nuclear translocation of NFκB, and subsequent generation of proinflammatory cytokines such as TNFα and interleukins." (PMID 40143165, 2025).
Sepsis (continued). "In Porphyromonas gingivalis LPS-induced sepsis in mice, TLR4 caused cardiac dysfunction by activating NADPH oxidase-4, increasing ROS, stimulating calmodulin-dependent protein kinase-II with phosphophorylation of RyR2 and of phospholamban, a negative regulator of SR Ca2+ uptake." (PMID 40649397, 2025). "Moreover, TLR4‐deficient mice have higher survival rate during lethal polymicrobial sepsis compared to mice with normal TLR4 expression." (PMID 39853914, 2025). "TLR4, associated with its downstream mediator myeloid differentiation primary response 88 (MyD88), is activated by LPS and regulates inflammation and apoptosis in RTECs during sepsis." (PMID 40148079, 2025). "In addition, calprotectin has been reported to act as a damage-associated molecular pattern (DAMP) during sepsis, exerting its effects through the Toll-like receptor 4 (TLR4) signaling complex." (PMID 41301767, 2025). "Dysregulated TLR4 signaling is a hallmark of immune disorders such as sepsis." (PMID 40421030, 2025). "TLR2 and TLR4 are the primary TLRs implicated in sepsis-related cardiac injury." (PMID 40386784, 2025). "Notably, BCG-vaccinated neonatal mice exhibited reduced TLR4/MyD88 signaling and suppression of pathways linked to granulocyte migration and recruitment, neutrophil adhesion and movement, compared to sepsis alone." (PMID 40307728, 2025). "This blockade of TLR4 signaling may effectively dampen the inflammatory response associated with viral infections and sepsis." (PMID 40333077, 2025). "High-throughput screening using the iTLR4 assay could identify new compounds that modulate TLR4 activity, offering therapeutic potential for conditions where TLR4 is implicated, such as sepsis, chronic inflammatory diseases, and certain cancers." (PMID 40959069, 2025). "Activation of macrophage TLR4 by bacterial endotoxins is important for the progression of sepsis, but the underlying mechanisms remain unknown." (PMID 39294473, 2024). "In sepsis, the cytotoxicity initiated by the eCIRP/TLR4 axis in CD4CD8αα IELs is associated with intestinal epithelial cell (IEC) death, which could lead to gut injury." (PMID 38302880, 2024). "TLR4 is a key signaling molecule in initiating the immune response to exogenous bacteria and endogenous damage-associated molecular patterns during endotoxemia or sepsis." (PMID 38549133, 2024). "In this regard, cells from patients with FMF had high levels of S100A8 and S100A9 alarmins but not cells from patients with other inflammatory disorders like sepsis, where these molecules act as ligands for TLR4 and cause strong inflammatory responses within tissues." (PMID 39335710, 2024). "Moreover, TLR2 and TLR4 polymorphisms are associated with a higher risk of staphylococcal or gram-negative infections, further underscoring the involvement of TLRs in sepsis." (PMID 38835761, 2024). "Species from seven genera were reported to function as human pathogens: Plesiomonas causes various highly infectious diseases including septicemia, meningitis, and colitis; Eubacterium rectum induces human colitis via the Toll-like receptor 4 (TLR4) pathway; Slackia spp." (PMID 39628718, 2024). "Furthermore, we demonstrated that the TLR4‐NF‐κB‐NO pathway was associated with Triad3A and responsible for the killing of intracellular mycobacteria in a tuberculosis sepsis model." (PMID 37506157, 2023). "Knockout of the TLR4 gene in C57BL/6 mice afford protection against sepsis-associated AKI." (PMID 36674930, 2023). "Moreover, the lncRNA CRNDE/miR-181a-5p/TLR4 axis has been shown to alter the pathogenesis of sepsis-associated inflammation." (PMID 36743692, 2023). "This heterogenous presentation of sepsis could be attributed to mutations in Toll-like receptor-4 (TLR-4), though this has been disputed." (PMID 37759732, 2023).
Sepsis (continued). "The remarkable importance of TLR2 and TLR4 in our immune system and in modulating our response to infection suggested potential roles of their important variants, Arg753Gln and Asp299Gly, in increasing susceptibility to infection and sepsis as well." (PMID 36142893, 2022). "Identification of the role of TLR2 and TLR4 polymorphisms in developing infection and sepsis could allow early prediction, prevention, and management of these serious diseases." (PMID 36142893, 2022). "LPS-mediated CD14 activates Src-Tyrosine kinase to phosphorylate caveolin-1 at Tyr in endothelial cells, Cav-1 specific.In sepsis-induced lung inflammation and injury, LPS triggers the association of Cav-1-pTyr14 with TLR4, thereby inducing NF-kappa B signaling for proinflammatory cytokines." (PMID 36559147, 2022). "This could have implications for improving outcomes in acute inflammation and sepsis or in chronic disease as both CD11b and TLR4 are associated with these processes." (PMID 34400791, 2022). "In addition to the recognition of pathogen-associated molecular patterns, TLR4 also recognize non microbial endogenous molecules, which has expanded this field beyond sepsis into conditions of autoimmunity and inflammation." (PMID 36510147, 2022). "As LPS is the major exogenous ligand for TLR4, it might be that in vivo, morphine increases LPS which activates TLR4, as part of an underlying sepsis induced by the opioid." (PMID 36428812, 2022). "Both miR-15a and miR-16 are encoded in the same chromosomal region (13q14.3) and experimentally recognized to take part in regulation and decrease of macrophage-mediated phagocytosis in bacterial infection by targeting Toll-like receptor 4–associated pathways, which can aggravate sepsis." (PMID 35305556, 2022). "Although the exact mechanism underlying renal dysfunction in sepsis remains unknown, there is strong experimental evidence supporting the prominent role of the toll-like receptor 4 (TLR-4), which is expressed in the kidney." (PMID 35160068, 2022). "The TLR4 downstream adaptor MyD88 is a key adaptor in interleukin-1 receptor (IL-1R) signaling, and a study demonstrated that MyD88-deficient mice exhibit resistance to LPS-induced sepsis." (PMID 36439213, 2022). "This lncRNA could promote inflammatory responses and aggravate sepsis-associated hepatic damage through the Let-7a/TLR4 axis." (PMID 34956235, 2021). "Lipopolysaccharide (LPS) is an endotoxin originated from the gram-negative bacteria E. coli and was initially confirmed as a Toll-like receptor 4 (TLR4) ligand, which causes a rapid and powerful inflammatory reaction leading to sepsis or multiple organ failure." (PMID 34445058, 2021). "The inflammatory response in sepsis is initiated by the recognition of pathogen-associated molecular patterns, such as lipopolysaccharide (LPS), by pattern recognition receptors, principally Tool-like receptor 4 (TLR4), on the epithelial cell surface." (PMID 34076840, 2021). "More and more studies have indicated that dexmetomidine may reduce the degree of acute liver injury caused by sepsis by inhibiting the release of pro-inflammatory cytokines mediated by TLR-4 signal pathway." (PMID 33558888, 2021). "However, to date, a few studies have elucidated the effects of sesamin on the progression of sepsis via TLR4-associated signalling." (PMID 32893702, 2020). "However, over activation of TLR4 can lead to serious inflammatory reaction and cause damage to the body, such as in sepsis." (PMID 33597886, 2020). "However, excessive or inappropriate TLR4 activation has been directly implicated in many inflammatory and autoimmune diseases, such as ischemia, sepsis, asthma, hepatitis, neuropathic pain, neurodegenerative diseases." (PMID 33597886, 2020).